IL2 (interleukin 2)
Diseases named in the same sentence as IL2 in open-access papers (continued):
Sharing a sentence is not in itself a finding about the gene and the disease.
metastatic melanoma (continued). "In PIVOT IO 001 (NCT03635983), the combination of the investigational interleukin-2 agonist bempegaldesleukin (BEMPEG) with nivolumab (NIVO) had no added clinical benefit over NIVO monotherapy in unresectable/metastatic melanoma." (PMID 39025948, 2024). "Concluding from a meta-analysis involving 13 trials (published from 1988 to 2016), TIL+ recombinant IL-2 treatment for metastatic melanoma, excluding uveal melanoma, was found to have an ORR of 41% and an overall complete response rate (CRR) of 12%." (PMID 39013849, 2024). "IL-2, known for its capacity to boost T-cell responses, has been approved for metastatic renal cell carcinoma and metastatic melanoma, demonstrating the feasibility of enhancing the immune system to fight cancer." (PMID 39034318, 2024). "Further in 1998, HD IL-2 therapy was also approved for the treatment of metastatic melanoma (MM) based on a 16% ORR with 6% CRs, 10% PRs, and 5.9 months median response duration for PRs among 270 patients with MM from 8 clinical trials." (PMID 39114660, 2024). "Recombinant interleukin 2 (IL-2, aldesleukin) was approved for the treatment of metastatic melanoma and renal cell carcinoma over two decades ago." (PMID 38887559, 2024). "Due to their key role in the immune system, interleukin-2 (IL-2), for example, has been used to treat metastatic melanoma and renal cell carcinoma." (PMID 38476371, 2024). "Results from this study should be taken into consideration and interrogated further in future studies, with the goal of attaining therapeutic synergy between IL-2 agonists and immune checkpoint inhibitors in patients with unresectable/metastatic melanoma." (PMID 39025948, 2024). "Early uses of recombinant IL-2 in patients with metastatic melanoma led to remarkable anti-tumor responses, though objective responses were limited to 16% of patients." (PMID 38928238, 2024). "Immunotherapy based on interleukin-2 (IL-2) is an FDA-approved treatment option for metastatic melanoma and renal cell carcinoma." (PMID 38337114, 2024). "A study involving 195 metastatic malignant melanoma patients observed prolonged OS in patients who received immunotherapy (IL-2, anti-PD-1, or anti-CTLA-4) and were taking pan beta blockers experienced." (PMID 38850359, 2024). "This treatment has been recently approved by the Food and Drug Administration (FDA) for refractory metastatic melanoma, underscoring the importance of IL-2 in advancing personalized cancer therapy." (PMID 38928238, 2024). "Patients with metastatic melanoma who received a combination of interleukin-2 and gp100 peptide cancer vaccine had improved clinical responses than patients who received interleukin-2 alone." (PMID 38515636, 2024). "A previous study demonstrated that the use of a lower dose of interleukin 2 (IL-2) in the context of adoptive cell therapy with TILs was well tolerated and clinically effective in metastatic melanoma patients." (PMID 37251931, 2023). "Prior to their discovery, metastatic melanoma had become resistant to conventional radiotherapy and chemotherapy, and the most promising option was high-dose interleukin-2." (PMID 37442992, 2023). "Among the cytokines or cytokine/receptor pathways used in clinical trials for the treatment of metastatic melanoma we must mention IL-2, IL-8, IL-10, IL-12, IFN-α and TNF-α, as well as tumor growth factors." (PMID 36768978, 2023). "A phase II clinical trial has shown that in metastatic melanoma, patients treated with IL-2+SBRT have a higher disease control rate compared with IL-2 monotherapy." (PMID 38259489, 2023). "Patients with metastatic melanoma or metastatic renal cell carcinoma were the most responsive to high-dose IL-2 administration, while only rare objective responses were observed in patients with other tumor types." (PMID 37174716, 2023).
metastatic melanoma (continued). "For this experiment, we chose to only use the TPV/Δ66R/mIL-2 recombinant as it had demonstrated efficacy IT for the reconstituted animals, and IV-delivered interleukin-2 has been FDA approved since 1998 for the treatment of stage IV metastatic melanoma." (PMID 37628585, 2023). "High-dose IL-2 demonstrates potential, inducing objective responses in up to 15% of patients with metastatic melanoma and RCC, with some patients achieving durable complete responses." (PMID 37516849, 2023). "One class of IL2 therapeutics seeks to improve upon the properties of Proleukin, a marketed IL2 therapeutic for the treatment of metastatic melanoma and renal cell carcinoma." (PMID 36839922, 2023). "In contrast, patients in another study treated with standard IL-2 had positive ORR values of 57.14% ORR for patients with metastatic melanoma and 100% ORR for patients with metastatic kidney cancer." (PMID 36936961, 2023). "The FDA approved the use of high-dose interleukin-2 (IL-2) therapy in 1992 for metastatic renal cell carcinoma and in 1998 for the treatment of metastatic melanoma." (PMID 36874133, 2023). "Twenty participants with metastatic melanoma who took part in Steven Rosenberg’s clinical trial were infused with a cultured suspension of TILs and IL-2." (PMID 36768737, 2023). "Dating back to the 1990s, IL-2 was approved as the first cancer immunotherapy drug for metastatic renal cell carcinoma and metastatic melanoma." (PMID 36936961, 2023). "The FDA approved the use of high-dose IL-2 In 1992 for the treatment of metastatic renal cell carcinoma, and in 1998 for metastatic melanoma." (PMID 37256141, 2023). "The FDA has approved the use of IL-2 as a monotherapy for metastatic renal cell carcinoma and metastatic melanoma." (PMID 36874011, 2023). "A number of different intralesional immunotherapies have been studied in the treatment of metastatic melanoma, such as interleukin-2 (IL2), Bacillus Calmette-Guerin (BCG), checkpoint inhibitors, and oncolytic viruses, all to variable degrees of success." (PMID 37182189, 2023). "Interleukin-2, a potent T cell activator, is approved for the treatment of renal cell carcinoma and metastatic melanoma, where high-dose regimens produce significant clinical responses but are hindered by severe toxicity." (PMID 37869009, 2023). "High-dose interleukin-2 (HD IL-2) and pembrolizumab are each approved as single agents by the U.S. F.D.A. for the treatment of metastatic melanoma." (PMID 36845705, 2023). "In 1998, interleukin-2 (IL-2) was the first immunotherapy agent approved for use in patients with advanced metastatic melanoma." (PMID 36831449, 2023). "Prior to the emergence of ICIs, cytokines, including IFN-α and interleukin-2 (IL-2), were identified as some of the initial efficacious treatments for advanced metastatic melanoma." (PMID 37627153, 2023). "The objectives of this study were to characterize the safety profile of IL-2 in combination with pembrolizumab in patients with unresectable or metastatic melanoma." (PMID 36845705, 2023). "Four-hundred and nine patients with metastatic melanoma or renal cancers were treated with a high dose of IL-2 (720,000 IU/kg) between September 1985 and November 1996 with a median potential follow-up of 7.1 years." (PMID 37174716, 2023). "Approval of IL-2 treatment for metastatic melanoma and renal cancer by the US Federal and Drug Administration (FDA) kickstarted a new era of cancer therapy and brought the immunotherapy in the spotlight." (PMID 35720306, 2022). "The U.S. FDA approved IL-2 in 1992 for the treatment of metastatic renal cell carcinoma, and in 1998, subsequently, it was later approved for metastatic melanoma." (PMID 36135216, 2022). "The first immune therapy developed for metastatic melanoma was the interleukin-2 (IL2), characterized by a partial rate of effectiveness." (PMID 35898688, 2022).
metastatic melanoma (continued). "Recently, in a clinical trial, seven of 11 patients with metastatic melanoma who received a combination treatment of TILs, HD IL-2, and vemurafenib experienced an objective clinical response, two of which achieved a complete response." (PMID 36077696, 2022). "Since Rosenberg and his colleagues published their research, the regimen of TILs combined with IL-2 has been used in the treatment of patients with metastatic melanoma for decades." (PMID 36077696, 2022). "In patients with metastatic melanoma, treatments based on high doses of pro-inflammatory cytokines, such as IL-2, IL-12 and IFN⍺, decrease the disease burden, but display modest anti-tumor activity." (PMID 36411434, 2022). "Recombinant IL-2 monotherapies have already been tried in patients with metastatic melanoma or metastatic renal carcinoma in the eighties with mild success." (PMID 36066630, 2022). "IL2 represents the first effective immunotherapeutic agent, benefiting patients with metastatic melanoma and advanced non-Hodgkin’s lymphomas." (PMID 35799600, 2022). "Treatment with HD IL-2 in patients with metastatic melanoma has demonstrated an ORR up to 15%, with approximately 5% of patients developing a CR and a part of the responders showing durable long-term responses." (PMID 35053435, 2022). "BEMPEG (Bempegaldesleukin), a pegylated version of IL2, had advanced to the third clinical trial stage in combination with Nivolumab for metastatic melanoma (NCT03435640)." (PMID 36135216, 2022). "The first protocol used involved the use of interleukin 2 (IL-2) for the treatment of metastatic melanoma." (PMID 35628540, 2022). "Until the last decade, the treatment options for advanced or metastatic melanoma included surgical resection, systemic chemotherapy (dacarbazine), and elevated doses of interleukin 2 (IL-2)." (PMID 36143375, 2022). "The combination of adoptive T cell therapy with conditioning chemotherapy and high-dose IL2 showed a 55% ORR in a cohort of 101 patients with previously treated metastatic melanoma." (PMID 35742834, 2022). "A study from Copenhagen demonstrated that LD IL-2 combined with a TIL infusion resulted in two out of six patients with metastatic melanoma having durable objective responses." (PMID 36077696, 2022). "Since the early 1990s, high-dose IL-2 therapy has been used to boost anti-tumor immune responses in metastatic melanoma and renal cell carcinoma." (PMID 35874707, 2022). "Historically, PBMC were cultured with IL-2 for a few days and then infused into the patient (with renal cell carcinoma or metastatic melanoma) together with high dose IL-2 that provoked huge side effects such as a serious vascular leak syndrome." (PMID 35054985, 2022). "Currently, Aldesleukin (recombinant human IL-2) is approved by the FDA for treating patients with metastatic melanoma and metastatic renal cell carcinoma." (PMID 36297474, 2022). "Until 2010, alternatives for the treatment of metastatic melanoma were mainly limited to the use of dacarbazine, high-dose IL-2 and bio-chemotherapy, despite its toxicity." (PMID 36286442, 2022). "The standard method of exposing tumor-derived lymphocytes to high dose IL-2 in vitro followed by rapid expansion in a mixed feeder population, was found to be an effective treatment option for patients with refractory metastatic melanoma." (PMID 35664731, 2022). "Repurposing recombinant IL-2 (aldesleukin) for treating human cardiovascular disease is of interest, although currently its licensed indication is limited to metastatic melanoma and metastatic renal cell carcinoma." (PMID 34503682, 2021). "Despite having FDA approval for RCC and metastatic melanoma, poor response rates and adverse side effects have curtailed the widespread adoption of HD IL-2 therapy." (PMID 34790830, 2021). "Most importantly, low dose IL2 combined with other immunotherapy demonstrated benefit in patients with metastatic melanoma." (PMID 34238310, 2021).
metastatic melanoma (continued). "Simultaneously, high-dose IL-2 was developed for patients with unresectable regional or metastatic melanoma." (PMID 34885172, 2021). "TIL-based ACT in combination with high doses of IL-2 has been widely studied in patients with metastatic melanoma and has showed significant improvement in clinical outcomes." (PMID 34066067, 2021). "Second, a Phase III trial in metastatic melanoma that tested the peptide vaccine in combination with high-dose IL-2 versus IL-2 alone, showed significant improvement in overall response rates and progression-free survival in patients who received the vaccine." (PMID 34830221, 2021). "While IL-2 was the first FDA approved immunotherapy for metastatic melanoma and metastatic renal cancer, the dual functionality of IL-2 has been reported to regulate immunosuppressive environment intratumorally." (PMID 34012451, 2021). "The best overall response rate (ORR) to high-dose IL-2 was 22.5% for metastatic melanoma, with four complete responses and five partial responses." (PMID 34804979, 2021). "IL-2 is an approved, effective therapy for metastatic melanoma, and the antitumor effects of IL-2 and IL-15 have been explored in combination with other treatments." (PMID 33910015, 2021). "In a retrospective study, the overall objective response rate in patients with metastatic melanoma treated with IL-2 was 16% (N=270), with 17 complete responses and 26 partial responses." (PMID 34804979, 2021). "Administration of interleukin-2 (IL-2) in patients with metastatic melanoma has shown that some immune cell populations exhibit elevated levels of activated STAT5 correlated with increased transcription of CISH and PIM-1." (PMID 34067095, 2021). "In 270 patients who received high-dose IL-2 therapy for the treatment of metastatic melanoma, the overall response rate was 16%, with 17/270 complete responses and 26/270 partial responses." (PMID 34790830, 2021). "High-dose IL-2 is widely recognized in several studies to produce durable and favorable responses in metastatic melanoma, including patients with brain metastases." (PMID 33466236, 2021). "A radiopharmaceutical that has been investigated in patients affected by metastatic melanoma and before and after immunotherapy with ipilimumab is [99mTc]Tc-interleukin-2 ([99mTc]Tc-IL2)." (PMID 33537909, 2021). "In fact, it was initially tested in refractory metastatic melanoma patients, in which the use of TILs that were extracted and then rapidly expanded with feeder cells and high doses of IL-2, revealed capable of generating enough cells for reinfusion." (PMID 33530328, 2021). "High-dose interleukin-2 (HD IL-2) has curative potential in metastatic melanoma (MM) and renal cell carcinoma (RCC)." (PMID 34777395, 2021). "A phase I study for the combination of the IL-2 immunocytokine and the chemotherapeutic agent dacarbazine in metastatic melanoma exhibited low rates of severe toxicity, mainly grade 4 leukopenia/neutropenia and grade 3 hypotension." (PMID 33803078, 2021). "The PIVOT-02 study (NCT02983045) exhibited the safety and efficacy of bempegaldesleukin, a CD122-preferential interleukin-2 pathway agonist, plus nivolumab in the first-line treatment of metastatic melanoma." (PMID 34804979, 2021). "Interleukin 2 administration resulted in objective response rates of 14% and 16% in metastatic renal cell carcinoma (mRCC) and metastatic melanoma patients, respectively." (PMID 33803078, 2021). "In 1998, the Food and Drug Administration (FDA) approved high-dose IL-2 for the treatment of patients with metastatic melanoma." (PMID 34804979, 2021). "In another retrospective study, high-dose IL-2 treatment maintained antitumor efficacy in patients with metastatic melanoma who had progressed after receiving PD-1 and PD-L1 suppression." (PMID 34804979, 2021). "Approved for treatment of renal cell carcinoma and metastatic melanoma, IL-2 is a potent T cell activator." (PMID 34168629, 2021).
metastatic melanoma (continued). "One obvious candidate is IL-2 which is approved for the treatment of metastatic renal cell cancer and metastatic melanoma." (PMID 37849947, 2021). "After initial treatment with chemotherapy, the patients bearing metastatic melanoma were treated by administration of IL-2 and TILs." (PMID 33807011, 2021). "Helen's team previously suggested that the combination between vinorelbine and IL-2 is considered as second-line therapy for metastatic melanoma." (PMID 34745259, 2021). "A comprehensive report published in 1987 by the NCI’s Surgery Branch documented objective responses to high-dose IL-2 and regression of tumors in patients with metastatic melanoma and renal cell cancer." (PMID 32283684, 2020). "IL-2 can stimulate cytotoxic T lymphocytes and is a longstanding treatment option for metastatic melanoma patients." (PMID 32742470, 2020). "The adoptive transfer of TILs can induce sustained antitumor responses in patients with metastatic melanoma in combination with lymphodepletion and IL-2 administration." (PMID 32314731, 2020). "IL2 was one of the earliest FDA-approved immunotherapies for metastatic melanoma and renal cell cancer." (PMID 33381115, 2020). "TIL therapy was tested in metastatic melanoma patients as early as 1988, with results showing objective regression in 60% of patients who were previously untreated with IL-2." (PMID 32679922, 2020). "Despite this, therapy related mortality remains very low, and IL‐2 treatment can offer significant improvements to survival, particularly in patients with metastatic melanoma." (PMID 32480431, 2020). "Infusion of IL-2 in multiple cycles at different doses in metastatic melanoma patients proved that the immune system can completely eradicate cancer cells under certain conditions which have led to the first success in cancer immunotherapy." (PMID 32742470, 2020). "For many decades, the most common treatment regimens for metastatic melanoma were the systemic immuno-stimulating cytokines such as interleukin-2 (IL-2) and interferon-alpha (IFN-α)." (PMID 33313405, 2020). "The first clinical studies in this area, over 3 decades ago, used IL‐2‐expanded autologous tumor‐infiltrating lymphocytes (TIL) to treat metastatic melanoma." (PMID 32480431, 2020). "High-dose recombinant interleukin 2 (IL2) therapy has been shown to be successful in renal cell carcinoma and metastatic melanoma." (PMID 32560387, 2020). "A pilot study of stereotactic body radiation therapy (SBRT) followed by high-dose interleukin-2 (IL-2) showed a higher than anticipated objective response rate (ORR) among patients with metastatic melanoma (MM)." (PMID 32467299, 2020). "In this regard, histamine is being administered as an adjuvant to immunotherapy with IL-2 for the treatment of patients with metastatic melanoma and acute myeloid leukaemia, demonstrating clinical benefits." (PMID 31748740, 2020). "To date, a small handful of studies have been reported using intralesional IL2 alone for metastatic melanoma." (PMID 32455916, 2020). "The first immunotherapy regimen developed used interleukin 2 (IL-2) to treat patients with metastatic melanoma." (PMID 32260561, 2020). "Recombinant IL2 has shown encouraging results in the treatment of metastatic melanoma and renal cell carcinoma." (PMID 33110477, 2020). "High serum levels of pre-treatment CRP predict resistance to IL-2 therapy in patients with metastatic melanoma." (PMID 32610601, 2020). "IL-2, a multifunctional cytokine, is essential in differentiation and proliferation of T cells, NK, macrophages and B cells, which is effective in metastatic melanoma and renal carcinoma." (PMID 34138136, 2020). "Given its ability to stimulate T cell proliferation, IL-2 has been used as a cancer immunotherapy since the 1980s, when it was described in the use of metastatic melanoma and renal cell carcinoma." (PMID 33704189, 2020).